TLR2 (toll like receptor 2)
Diseases named in the same sentence as TLR2 in open-access papers (continued):
Sharing a sentence is not in itself a finding about the gene and the disease.
Alzheimer disease (continued). "Toll-like receptor 2 (TLR2) represents a reasonable functional and positional candidate gene for Alzheimer's disease (AD) as it is located under the linkage region of AD on chromosome 4q, and is functionally involved in the microglia-mediated inflammatory response and amyloid β (Aβ) clearance." (PMID 21989233, 2011). "Toll-like receptor 2 (TLR2) represents a reasonable functional and positional candidate gene for Alzheimer's disease (AD) as it is located under the linkage region of AD on chromosome 4q, and functionally is involved in the microglia-mediated inflammatory response and amyloid-β clearance." (PMID 21989233, 2011). "In mild cognitive impairment and very early-stage Alzheimer disease patients, monocytes have been suggested to be the sources of increased oxidation products, exhibiting significantly increased chemotaxis and cytokine production in response to Toll-like receptor 2 and 4 stimulation." (PMID 38798352, 2024). "Hyperactivation of monocytes and macrophages in response to TLR2 and TLR4 stimulation in ‘mild cognitive impairment’ patients contributes to the progression of Alzheimer’s disease." (PMID 36140198, 2022). "It is shown that fibrillar amyloid β (Aβ) can directly interact with Toll-like receptor 2 (TLR2), TLR4, and CD14 to induce microglial Aβ phagocytosis at the initial stages and neuroinflammatory responses at the late stages of Alzheimer's disease." (PMID 25563673, 2014). "In Alzheimer’s disease (AD), soluble amyloid-β oligomers and fibrils interact with cell-surface receptors (e.g., integrin, CD14, and the Toll-like receptors TLR2 and TLR4) in microglial cells, and these interactions can also trigger a neuroinflammatory response." (PMID 30319390, 2018). "While TLR2, TLR4, TLR5 and TLR10 might be involved in the pathogenesis of systemic sclerosis, TLR activation can have both destructive and protective effects on Alzheimer ́s disease (AD)." (PMID 33499143, 2021).
myocardial infarction (36 papers, 2010 to 2025). Gross necrosis of the myocardium, as a result of interruption of the blood supply to the area, as in coronary thrombosis. "In the context of coronary artery disease – a major risk factor for HF – TLR2/4 expression on monocytes is elevated during acute myocardial infarction (AMI)." (PMID 40901835, 2025). "For example, it has been demonstrated that TLR2-deficient mice exhibit higher fractional shortening and survival after myocardial infarction in comparison to wild-type animals." (PMID 24611063, 2014). "Among TLRs, TLR2, 3, 4 and 9 have been widely reported to be associated with the occurrence of various cardiovascular diseases, including heart failure, dilated cardiomyopathy, myocardial infarction." (PMID 41552821, 2025). "TLR2 activates inflammatory responses by activating the TLR2-Myd88-NF-κB pathway, also activates immune cells to promote apoptosis, and is associated with the severity of coronary artery disease, plaque instability, and myocardial infarction in myocardial injury." (PMID 38764052, 2024). "The main TLRs expressed in myocardial cells include TLR2, TLR3, and TLR410, wherein TLR4 is involved in myocardial injury caused by myocardial infarction." (PMID 38159178, 2024). "In cardiovascular diseases, the downregulation of TLR2 expression in myocardial infarction models has demonstrated a protective effect." (PMID 38566986, 2024). "Previous studies have confirmed that the expression of TLR2 in left atrial blood samples of AF patients is significantly increased and that TLR2 has the potential to be a new biomarker for new-onset AF after acute myocardial infarction." (PMID 37180786, 2023). "For example, LINC00936 and LINC00528 were recently predicted to interact with TLR2 and the Toll-like receptor signaling pathway in acute myocardial infarction." (PMID 35945487, 2022). "Nevertheless, extra work is essential to validate the specific mechanism of TLR2 in myocardial infarction and to clarify its application value role in clinical diagnosis and forensic pathology identification." (PMID 35840880, 2022). "We performed an integrated WGCNA and validated that TLR2 and CD14 were closely associated with the severity of coronary artery disease, plaque instability and the prognosis of heart failure after myocardial infarction." (PMID 33574831, 2020). "β-Caryophyllene at doses of 100 and 200 mg/kg lessened post- myocardial infarction TLR activity measured as the protein content of TLR2 (A), TLR4 (B), MyD88 (C), and TRIF (D) in the heart tissue (p < 0.05)." (PMID 31109132, 2019). "In the model of myocardial infarction, pharmacological inhibition of TLR2 or TRL4 can decrease monocyte inflow into the infarcted region, decrease the infarct area, and enhance myocardial remodeling." (PMID 31772617, 2019). "Our results showed that ISO-induced myocardial infarction is accompanied by significant escalations in levels of the TLR2, TLR4, MyD88, and TRIF, enhancing subsequent inflammatory mediator signaling." (PMID 31109132, 2019). "After myocardial infarction, gene expression levels of the plasma membrane localized Tlr2 and Tlr6 were significantly increased when compared to their healthy controls." (PMID 29538462, 2018). "In this study, we observed highly increased gene expression levels of Tlr1, Tlr2, Tlr6, Tlr7, Tlr8, Tlr9 as well as Irf7 in the scar tissue after myocardial infarction, indicating their relevance to a proper cardiac wound healing." (PMID 29538462, 2018). "On the other hand, miR-327 was reported to indirectly suppress the TLR4 and TLR2 signaling pathways, and subsequently resulted in reduced myocardial infarct size and alleviated inflammation." (PMID 30513647, 2018). "An involement of Toll-like receptor 2 (TLR2) has been established in cardiac dysfunction after acute myocardial infarction; however, its role in chronic pressure overload is unclear." (PMID 28835616, 2017).
myocardial infarction (continued). "Similar to TLR2, TLR4-deficient mice show after myocardial infarction enhanced LV function and improved remodeling leading to significantly increased survival of TLR4-deficient mice." (PMID 24611063, 2014). "There is a growing body of evidence linking TLRs, particularly TLR2 and TLR4, to the deleterious inflammatory effects seen in ischemia/reperfusion injury associated with trauma, stroke, myocardial infarction, and solid organ transplantation." (PMID 20628516, 2010). "TLR4 and TLR2 activation following myocardial ischemic injury triggers the NF-kappa B pathway and subsequent expression of pro-inflammatory genes, inducing an inflammatory cascade, increasing myocardial infarction size, and impacting cardiac remodeling." (PMID 39024234, 2024). "Toll-like receptor 2 (TLR2), an important mediator in innate immune system, is associated with myocardial infarction and could be selectively suppressed by curcumin, thus curcumin may prevent and treat myocardial infarction." (PMID 37191432, 2023). "Inhibition of TLR2 or TLR4 can reduce myocardial infarction area and inhibit myocardial remodeling." (PMID 36407421, 2022). "TLR2 is also directly related to heart failure after myocardial infarction." (PMID 33574831, 2020). "Through the generation of chimeric mice, the authors also showed that TLR2 expressed on renal parenchyma was the key cell type involved in renal tissue injury which is in contrast to the findings in myocardial infarction model where neutrophils and monocytes were the key cell types mediating injury." (PMID 20628516, 2010). "In a mouse model, TLR2 was involved in cardiac remodeling after myocardial infarction (MI), and preservation of cardiac function, increased survival rate, and attenuation of myocardial fibrosis after MI in TLR2 KO mice were observed." (PMID 29576748, 2018). "This research sought to investigate the clinical significance of level changes of TLR2, TLR3, TLR4, TNF-α, sTNFR-1, sTNFR-2, EPCs, and VEGF in elderly patients with recurrent myocardial infarction after coronary stent implantation." (PMID 35425840, 2022). "Elevated expression and activity of CD14, TLR2, and TLR4 correlate with advanced atherosclerotic lesions, followed by plaque rupture and myocardial infarction." (PMID 34829669, 2021). "We analyzed the expression levels of LILRB2, TLR2, NCF2, and S100A9 in AMI samples (blood samples on the first day of myocardial infarction) and stable coronary artery disease (CAD) controls." (PMID 34490057, 2021). "In the treatment of myocardial infarction, we have obtained key targets of Yixinyin, which are ALDH2, C5AR1, FOS, IL1B, TLR2, TXNRD1." (PMID 34799616, 2021). "Levels of TLR2, TLR3, TLR4, TNF-α, sTNFR-1, and sTNFR-2 were remarkably increased (P < 0.001), and EPCs and VEGF were remarkably lowered (P < 0.001) in the elderly patients with recurrent myocardial infarction after coronary stent implantation." (PMID 35425840, 2022). "Expressions of TLR2, TLR3, and TLR4 were demonstrated in atherosclerotic lesions and led to the development of the atherosclerotic lesions, atherosclerotic arterial occlusion, and acute myocardial infarction." (PMID 35425840, 2022). "TLR4, TLR2, MyD88, and TRIF protein levels via western blot in the heart tissue were measured following ISO-induced myocardial infarction to determine whether β-caryophyllene could suppress TLR activity through MyD88 down-regulation." (PMID 31109132, 2019). "Interestingly, post myocardial infarction TLR and IRF gene expression was almost exclusively increased in the infarct zone after myocardial ischemia (Tlr2, Tlr3, Tlr6, Tlr7, Tlr9, Irf3, Irf7)." (PMID 29538462, 2018). "In the heart, TLR2 and TLR4 are perhaps involved in the host response to myocardial infarction." (PMID 23889805, 2013).
myocardial infarction (continued). "In this paper, we summarise the current state of knowledge linking TLR2 and TLR4 to I/R injury, including recent studies which demonstrate that therapeutic inhibition of TLR2 has beneficial effects on I/R injury in a murine model of myocardial infarction." (PMID 20628516, 2010). "Other lines of evidence support this hypothesis such as mice lacking a functional TLR2 gene had diminished cardiac fibrosis after myocardial infarction." (PMID 40181955, 2025). "Interestingly, short pretreatment with the TLR2 agonist Pam3 reduced chemokine CXCL1 release from cardiomyocytes, which limited subsequent leukocyte infiltration and could reduce myocardial infarct size and improve cardiac function after ischemia/reperfusion." (PMID 36761746, 2023). "Many previous reports showed that expressions of TLR2, TLR3, and TLR4 as proatherogenic receptors were related to the extent and severity of coronary heart disease and led to the development of the atherosclerotic lesions, atherosclerotic arterial occlusions, and acute myocardial infarction." (PMID 35425840, 2022).
colon carcinoma (35 papers, 2010 to 2025). "In contrast, it was indicated that inhibiting or knocking out TLR2, was associated with marked suppression of colon cancer cell proliferation." (PMID 37493814, 2023). "Because TLR2−/− mice developed significantly larger colonic tumors, we next examined WT and TLR2 deficient colons 14 days into the AOM-DSS regimen for the earliest transformative events during tumorigenesis." (PMID 20885960, 2010). "Here we demonstrate that TLR2-deficient mice develop more and larger colonic tumors than WT control mice after AOM-DSS treatment." (PMID 20885960, 2010). "Hence, high TLR2 expression is significantly associated with poor overall survival in colon cancer patients; a trend of association of weak TLR2 expression in the invasive front and in lymph node metastases and better disease-free survival was observed." (PMID 33321934, 2020). "A recent study confirmed that TLR2 knockout in mice showed a reduced tumor growth of colon cancer, and TLR2 downregulation in cancer cells reduces its proliferation in colorectal cell lines HCT116 and HT29." (PMID 38390872, 2024). "Among patients with colon cancer, the CT or TT genotypes in tested TLR2 SNP were correlated with a 45% or 38% increase of disease risk, respectively." (PMID 35877427, 2022). "The expression of TLR2 in colon cancer is significantly upregulated and the TLR2 agonists significantly enhance the proliferation, migration, and invasion of CRC cells." (PMID 34733783, 2021). "To clarify if BGN is secreted to cultured medium and serves as a potential ligand for TLR2/4 in colon cancer cells, we looked at BGN in HT-29 and LS174T cultured medium using the immunoprecipitation–Western blotting method." (PMID 32050430, 2020). "In fact, TLR2 activation enhances reactive oxygen species (ROS) production in colon cancer cells and consequently activates sterol regulatory element-binding protein-2 (SREBP2), a transcription factor involved in cholesterol biosynthesis and uptake." (PMID 33321934, 2020). "Intriguingly, pre-stimulation with a TLR2 agonist prior to colon cancer coculture induced upregulation of multiple interferon-inducible genes as well as MHC molecules in MCs." (PMID 30987352, 2019). "As such, MCs were pre-stimulated with a TLR2 agonist (FSL-1) prior to the coculture with HT29 colon cancer." (PMID 30987352, 2019). "For instance, the TLR2/MyD88 axis has been recognized as a critical regulator of self-renewal of mammary and intestine epithelium as well as breast and colon cancer tumorigenesis." (PMID 28662055, 2017). "We have previously reported on associations of TLR2 and TLR4 SNPs with colon cancer risk and survival and identified significant GEI of alcohol and TLR2 gene with colon cancer risk." (PMID 28956832, 2017). "The associations between TLR4 rs10759931 SNP and TLR4 expression in colon cancer tissues, TLR2-196 to TLR2-174del SNP, and TLR2 mRNA expression have been reported." (PMID 28912808, 2017). "Population studies have shown that specific polymorphism of TLR2 and TLR4 receptors significantly increases the risk of colon cancer development in individuals already loaded with other known environmental factors (obesity, smoking, etc.)." (PMID 24390484, 2014). "In conclusion, the obtained results exhibited that 5-FU nanogel has an excellent effect rather than the 5-FU which was confirmed by suppressing the proliferation of colon cancer via inhibition of the TLR2/ NF-κβ and PI3K/AKT/mTOR as well as lowering the expression levels of Ki-67." (PMID 37493814, 2023). "Furthermore, the expression of TLR2 protein was shown to be upregulated in colon cancer and significantly correlated with a low overall survival rate of patients with colon cancer." (PMID 35937402, 2022). "However, the expression level of TLR2 or TLR4 is only slightly increased in colon cancer samples according to the GENT2 database." (PMID 32050430, 2020).
colon carcinoma (continued). "Indeed, TLR2 expression is further enhanced in colon cancer cells resistant to chemotherapy drugs such as 5-fluorouracil and oxaliplatin." (PMID 33321934, 2020). "TLR2 is required for the B. fragilis-mediated protection against colon cancer." (PMID 30429227, 2018). "Fifteen genes (DUSP2, INFGR1, IL6, IRF2, JAK2, MAP3K10, MMP1, NFkB1A, NOS2A, PIK3CA, SEPX1, SMAD3, TLR2, TYK2, and VDR) were associated with colon cancer mortality (PARTP <0.05); JAK2 (PARTP = 0.0086), PIK3CA (PARTP = 0.0098), and SMAD3 (PARTP = 0.0059) had the strongest associations." (PMID 25541970, 2014). "Fifteen genes (DUSP2, INFGR1, IL6, IRF2, JAK2, MAP3K10, MMP1, NFkB1A, NOS2A, PIK3CA, SEPX1, SMAD3, TLR2, TYK2, and VDR) were significantly associated with colon cancer mortality at the <0.05 level; an additional 15 genes had gene PARTP values between 0.05 and 0.10." (PMID 25541970, 2014). "We also recently showed that Tlr2 is over-expressed in DMH-induced colonic tumors." (PMID 22242189, 2012). "To identify whether TLR2 or TLR4 is responsible for the silencing of immunosuppressive Siglec ligands, we analyzed changes in disialyl Lewisa or sialyl 6-sulfo Lewisx glycan expression by knocking down TLR2 or TLR4 by applying specific shRNA for TLR2 or TLR4 in colon cancer cells." (PMID 32050430, 2020). "Herein, as shown in Fig., a notable increase in the levels of TLR2 was observed in the rats injected with DMH and exposed to γ-IR to induce colon cancer supporting its role in colorectal pathogenesis." (PMID 37493814, 2023). "TLR4 and TLR2 enhance metastasis of colon cancers, whereas NOD1 promotes several gastrointestinal malignancies such as colon cancer, as well as head and neck and oral squamous cell carcinoma." (PMID 35130902, 2022). "Peptostreptococcus has been shown to induce TLR2 and TLR4 expression in colon cancer cells in culture, thus boosting levels of reactive oxygen species and cell proliferation." (PMID 33441939, 2021). "Expression of TLR2 and TLR4 receptor proteins on colon cancer cells were confirmed by immunohistochemistry." (PMID 24390484, 2014). "Reverse-transcription polymerase chain reaction was performed for detection of TLR2 and TLR4 mRNA in colon cancer and normal colon epithelial cells using commercially available primers." (PMID 24390484, 2014). "Recently, we showed that Tlr2, Tlr5 and CD180 (a Tlr subtype) genes are up-regulated in colonic tumors of 1,2 dimethylhydrazine (DMH)-induced rats, an experimental model for sporadic colon carcinogenesis." (PMID 22242189, 2012). "TLR2, TLR3, and TLR4 are overexpressed in most colon cancer cells." (PMID 40143078, 2025). "In addition to upregulating PD-L1, L. mesenteroides also activated Toll-like receptors (TLRs) and NOD-like receptors (NODs) pathways, specifically through TLR2 and NOD2, while also exerting a suppressive effect on autophagy in colon cancer cell lines." (PMID 38755413, 2024). "In this study, we investigated the impact of genetic variation in TLR1 and TLR2, which are the receptors for HMGB1, on the clinical outcomes of colon carcinoma (COAD) patients who underwent postoperative adjuvant chemotherapy, specifically those with regional lymph node metastatic COAD." (PMID 37945630, 2023). "Enhanced colonic tumor development is evidenced early on by significantly increased numbers of aberrant crypt foci (ACF) and increased IL-6, IL-17A, TNFα and phosphoSTAT3 expression in the intestinal microenvironment of TLR2−/− mice as compared to WT mice." (PMID 20885960, 2010). "The aim of the study was an evaluation of TLR2 and TLR4 expression on the surface of human colon cancer cells in primary culture with or without autologous peripheral blood mononuclear cells." (PMID 24390484, 2014).